TGFB2-OT1 (TGFB2 overlapping transcript 1)
Synonyms: FLJ11812
Gene: Long non-coding RNA gene on chromosome 1 (218,442,626 to 218,443,996, forward strand). Ensembl gene ENSG00000281453.
Diseases named in the same sentence as TGFB2-OT1 in open-access papers:
TGFB2-OT1 is named in the same sentence as 1 disease in open-access papers, as found by Europe PMC text mining. Sharing a sentence is not in itself a finding about the gene and the disease.
TGFB2-OT1 shares sentences with these, for which no sentence is quoted: infection (1 paper).